TMEM121B (transmembrane protein 121B)
Synonyms: CECR6
Tractability: Antibody: the Human Protein Atlas places it where antibodies can reach.
Gene: Protein-coding gene on chromosome 22 (17,116,297 to 17,121,367, reverse strand). Ensembl gene ENSG00000183307.
Subcellular location (Human Protein Atlas): Vesicles; Nucleoplasm; Plasma membrane
Genetic constraint (gnomAD): Loss-of-function variants: 14 observed, 11.03 expected, observed/expected ratio (o/e) 1.27, 90% interval 0.83 to 1.84. The synonymous counts are far from expectation, so gnomAD's model fits this gene poorly and the ratio says little. Missense variants: 850 observed, 588.46 expected, observed/expected ratio (o/e) 1.44, 90% interval 1.37 to 1.53. Synonymous variants: 458 observed, 290 expected, observed/expected ratio (o/e) 1.58, 90% interval 1.46 to 1.71.
Homologues: Orthologues: chimpanzee TMEM121B (100% identical), macaque TMEM121B (99% identical), rat Tmem121b (88% identical), mouse Tmem121b (87% identical), tropical clawed frog tmem121b (37% identical), dog TMEM121B (34% identical), zebrafish tmem121b (33% identical), Caenorhabditis elegans F13E9.11 (14% identical). Paralogues in human: CIMIP2B (8% identical).
Diseases named in the same sentence as TMEM121B in open-access papers:
TMEM121B is named in the same sentence as 1 disease in open-access papers, as found by Europe PMC text mining. Sharing a sentence is not in itself a finding about the gene and the disease.
TMEM121B shares sentences with these, for which no sentence is quoted: breast carcinoma (1 paper).